CD36 (CD36 molecule (CD36 blood group))
Diseases named in the same sentence as CD36 in open-access papers (continued):
Sharing a sentence is not in itself a finding about the gene and the disease.
Obesity (continued). "In addition, a large body of evidence suggests that CD36 is involved in pro-inflammatory polarisation of macrophages upon exposure to oxidised LDL cholesterol and therefore contributes to the low-grade inflammatory state observed in diet-induced obesity and MetSy." (PMID 30386406, 2018). "Some studies show that people with obesity have a lower oxidative capacity, but FAs oxidation and FAT/CD36 content are not affected; studies to confirm this is lacking." (PMID 36615118, 2022). "Chronic membrane-localization of CD36, but not other FFA transporters (FABP3, FATP1, or FATP4), enhances FFA uptake and intracellular lipid accumulation in obesity." (PMID 35954283, 2022). "Fatty acid uptake factors such as CD36, FATP2, and FATP5 actively function when excessive fatty acids are present owing to high fat intake or obesity, but not in normal conditions." (PMID 31640183, 2019). "However, there is no information on the effect of obesity on the mammary gland gene expression of SCD1, LPL, CD36, and PPARG1." (PMID 38133242, 2023). "Finally, the detailed mechanism of how obesity promotes lipid accumulation in LNM and the role of LPL/CD36 in this process were not investigated." (PMID 36397145, 2022). "While obesity appears to enhance FA transport and oxidation predominately in SSM by an increase of FAT/CD36, CS, and β-hydroxyacyl-CoA dehydrogenase activities with unaltered CPT1, the absence of obesity and presence of T2DM lead to enhancement of FA oxidation only in IFM by CPT-I." (PMID 28850625, 2017).
Hepatic steatosis (258 papers, 2010 to 2025). Steatosis is a term used to denote lipid accumulation within hepatocytes. "This establishes a connection between Tspo loss, CD36 overexpression, and the impairment of autophagy in hepatic steatosis." (PMID 40195072, 2025). "We determined that CD36 deficiency attenuated HFD-induced hepatic steatosis while exacerbating MCD diet-induced steatohepatitis." (PMID 40110132, 2025). "Oil red O staining and triglyceride (TG) quantitative analysis also confirmed the conclusion that CD36 deficiency had reversed function on HFD or MCD diet-induced liver steatosis." (PMID 40110132, 2025). "Consistent with findings that hepatocyte-specific CD36 deficiency attenuated hepatic steatosis, we found that CCl4-treated ob/ob mice exhibited decreased CD36 protein." (PMID 39832399, 2025). "In summary, we uncover that drinking‐water supplementation of D‐mannose serves as a candidate T2D therapeutic, which rescued hepatic steatosis and diabetic bone loss through suppressing macrophage release of EVs based on metabolic control of CD36 expression." (PMID 41163804, 2025). "The up-regulation of CD36 attenuated the reduction of hepatic steatosis mediated by hepatic YBX1 deficiency in MASLD mouse models." (PMID 40083711, 2025). "Increased CD36 expression is implicated in the onset of hepatic steatosis in MASLD by promoting FA uptake." (PMID 40287434, 2025). "H&E staining shows that CD36 deficiency enhanced MCD-induced vacuolar lesions while reduced HFD-induced liver steatosis." (PMID 40110132, 2025). "Cluster of differentiation 36 (CD36) is highly expressed in the liver of patients with metabolic dysfunction-associated fatty liver disease (MAFLD) or metabolic dysfunction-associated steatohepatitis (MASH)." (PMID 40110132, 2025). "Hepatic CD36 is a membrane receptor involved in fatty acid uptake into the liver; it is responsible for hepatic steatosis and associated with systemic inflammation." (PMID 37836391, 2023). "Increased hepatic prolactin receptor expression is associated with decreased CD36 gene expression, thereby protecting against the development of hepatic steatosis." (PMID 36246929, 2022). "Recently, enhanced hepatic CD36 expression with age was shown to be associated with enhanced susceptibility to fatty liver in both mice and humans, which was also consistent with our current results." (PMID 36104831, 2022). "The activation of CD36 is involved in diet-induced hepatic steatosis and is linked to non-alcoholic fatty liver disease in humans." (PMID 32807074, 2020). "Our findings indicate that HFD-induced upregulation of CD36 expression is associated with increased sc and ab adiposity in addition to hepatic steatosis." (PMID 32807074, 2020). "PPARγ binds to the promoter of CD36 and increases its expression, which is associated with the development of hepatic steatosis." (PMID 32411189, 2020). "CD36 plays an important role in long-chain fatty acids uptake in liver and was associated with hepatic steatosis." (PMID 31379584, 2019). "Liver steatosis associated with increased expression of Cd36 was recently shown in mice exposed to low doses of BDE-47 perinatally and further kept on high fat diet for 14 weeks." (PMID 30294300, 2018). "CD36 is directly associated with the development of fatty liver and insulin resistance by modulating lipid uptake in hepatocytes." (PMID 29783731, 2018).
Hepatic steatosis (continued). "These metabolites have nutritional importance, obese mice treated with AERM (50 mg/kg) presented improvements in insulin resistance resulting in hepatic steatosis reductions associated with a strong inhibition of hepatic mRNA levels of CD36." (PMID 30135414, 2018). "Specifically, AhR sustained activation results in induction of fatty acid transport proteins and enhanced lipid uptake via activity of the fatty acid transporter CD36 to eventually cause accumulation of triglycerides leading to hepatic steatosis." (PMID 27045805, 2016). "Previous studies have shown that CD36-deficient mice are resistant to the induction of hepatic steatosis by alcohol and high-carbohydrate feeding." (PMID 26067236, 2015). "In support of the elevated TAG accumulation in Glmpgt/gt liver, the increased expression of PPARγ as seen in the Glmpgt/gt liver is a hallmark of hepatic steatosis, as it stimulates expression of lipogenic genes and the fatty acid transporter, CD36." (PMID 26047317, 2015). "Clinical evidence have demonstrated that CD36 is significantly increased in fatty liver and NASH patients, indicating of the association of the development of NAFLD with increased input of fatty acid in hepatocytes." (PMID 26572131, 2015). "Hepatic steatosis is associated with enhanced expression of CD36 in patients with non-alcoholic steatohepatitis." (PMID 24224011, 2013). "The primary purpose of this study was to investigate the role of CD36 in the pathogenesis of insulin resistance and hepatic steatosis caused by chronic HCV infection." (PMID 24016701, 2013). "Upregulation of CD36 was determined to be significantly associated with hepatic steatosis, hyperinsulinemia, and insulin resistance." (PMID 24224011, 2013). "Cd36 deficiency has been reported to protect mice against diet-induced hepatic steatosis and insulin resistance, while increased expression has the inverse effect." (PMID 23505504, 2013). "Lipid accumulation and marked hepatic steatosis in PXR-transgenic mice are associated with increased expression of the fatty acid translocase CD36 (also called FAT) and several accessory lipogenic enzymes, such as SCD-1 and long-chain free fatty acid elongase." (PMID 22187655, 2012). "The CD36 level in the liver correlates with hepatic triglyceride storage and secretion, suggesting that CD36 plays a causative role in the pathogenesis of hepatic steatosis." (PMID 22187655, 2012). "Taken together, the main findings of this study uncover an effective and potential T2D therapeutic by oral delivery of D‐mannose, which rescued both hepatic steatosis and diabetic bone loss through suppressing macrophage release of EVs based on metabolic control of CD36 expression." (PMID 41163804, 2025). "Besides, DNA hypomethylation of CD36 in primary human hepatocytes have been linked to the valproic acid-induced hepatic steatosis." (PMID 40164757, 2025). "However, it is also reported that CD36 deficiency enhanced HFD-induced liver steatosis by activating the transcription of MCP-1 in hepatocytes." (PMID 40110132, 2025). "Clostridia is one of the key intestinal microbiotas associated with liver steatosis, which may affect CD36 expression and lipid absorption." (PMID 40612138, 2025). "In addition to slc27a2a, previous work in zebrafish has implicated CD36 as a regulator of starvation-induced hepatic steatosis." (PMID 38467419, 2024). "Finally, we evaluated the expression of CD36, a fatty acid transporter whose overexpression has been associated with the development of hepatic steatosis and HCC." (PMID 38710924, 2024). "In addition, VPA treatment caused liver steatosis accompanied with the upregulation of CD36 and DGAT2." (PMID 37971986, 2023). "Thus, the loss of Wtap in the liver promotes hepatic steatosis mainly by increasing both lipolysis in eWAT and FFAs uptake in the liver due to increased expression of Igfbp1 and Cd36." (PMID 35927268, 2022).
Hepatic steatosis (continued). "Furthermore, NPY deficiency ameliorated HFD-induced fatty liver by regulating genes involved in fatty acid uptake and Tg synthesis, including Cd36, Lpl, Dgat2, and Cyp4a14." (PMID 34829968, 2021). "Increased CD36 expression has been shown to correlate with dyslipidemia and inflammatory hepatic stress as well as to enhance the susceptibility to develop hepatic steatosis and NAFLD." (PMID 34488621, 2021). "Thus, the loss of Mettl3 in the liver promotes hepatic steatosis mainly by increasing Cd36 expression." (PMID 34893641, 2021). "In this regard, we suggest that the reduced levels of hTG and hepatic steatosis observed in LPHs-treated mice could be caused by a lower fatty acids uptake, which is induced by the downregulation of hepatic CD36." (PMID 34439470, 2021). "CD36 directly contributes to the development and progression of fatty liver through regulating the uptake of fatty acids by hepatocytes, and the perturbation of hepatic CD36 attenuates fatty liver and associated inflammation in mice fed a high-fat diet." (PMID 33457418, 2020). "Indeed, we found that the deletion of ACE2 causes hepatic steatosis accompanied by an impairment of the CD36/sirtuin 1 axis, insulin signaling, and glucose metabolism in the liver." (PMID 28101297, 2016). "Excessive fat accumulation in WAT led to ectopic fat deposition in BAT and liver, giving rise to whitening of BAT and hepatic steatosis, and the latter was associated with up-regulated expression of genes for hepatic lipid sequestration, including Ppar-γ2, Cd36 and Mgat-1." (PMID 25768847, 2015). "Pparγ, an upstream positive regulator of Cd36 expression, is also linked to hepatic steatosis." (PMID 26085100, 2015). "A potential relation might lie in CD36 cells, whose deficiency was known to aggravate hepatic steatosis severity due to decreased FFA oxidation and, together with adiponectin, make a two-way direction in terms of potentiating their activity when it comes to the FFA oxidation process." (PMID 38455340, 2024). "Moreover, a number of previous studies have examined whether CD36 is associated with fatty liver disease." (PMID 38584832, 2024). "Similarly, FA translocase, also known as CD36, is a protein that orchestrates a critical role in enhancing uptake of FAs in hepatocytes as well as some other cell types in the liver, and has been implicated in the advancement of hepatic steatosis." (PMID 37744933, 2023). "It is widely acknowledged that CD36 plays a significant role in hepatic steatosis by facilitating fatty acid uptake, triglyceride storage, and secretion." (PMID 41157197, 2025). "Vroegrijk et al28 proposed that CD36−/− mouse liver steatosis is aggravated due to lower fatty acid uptake in muscle and adipose tissue, increased lipolysis in adipose tissue, and higher fatty acid flow to the liver." (PMID 39774047, 2025). "To further elucidate the mechanism underlying the effects of LG on DXM-induced fatty liver, we explored the role of AMP-activated protein kinase (AMPK) as a potential regulator of FASN and CD36 expression." (PMID 39820544, 2025). "To address this, we generated macrophage-specific S100a8-KO mice and observed a significant reduction in hepatic steatosis, accompanied by decreased expression of the fatty acid transporter CD36." (PMID 41178716, 2025). "In preclinical studies, the synthetic FXR agonist GW4064 reduced hepatic steatosis and limited weight gain by downregulating hepatic CD36 expression." (PMID 41438090, 2025). "Second, hepatic steatosis in Atp8b1 mutant liver coincided with increased expression of Cd36, which is involved in the uptake of medium‐ and long‐chain fatty acids." (PMID 40851490, 2025). "The current study provides evidence that elevated expression of CCN3 in the liver of macrophage-specific S100a8-KO mice inhibits CD36 expression and suppresses hepatic steatosis." (PMID 41178716, 2025).
Hepatic steatosis (continued). "Conversely, CD36 hepatocyte-specific knockout was protected from hepatic steatosis while improving systemic insulin sensitivity." (PMID 40110132, 2025). "Previous literature reported that BMAL1 deletion inhibits the expression of CD36 and peroxisome proliferator-activated receptor γ (PPARγ) and attenuates hepatic steatosis." (PMID 40083324, 2025). "PCSK9 can protect mice fed an HDL diet against hepatic steatosis and liver injury by inhibiting CD36 expression and fatty acid uptake." (PMID 39774047, 2025). "In ob/ob mice, systemic CD36 deficiency upregulates the level of prostaglandins and then inhibits the secretion of liver VLDL, thereby promoting liver steatosis." (PMID 39774047, 2025). "CD36-mediated fatty acid uptake plays a critical role in hepatic steatosis development, and its suppression is considered a promising therapeutic strategy." (PMID 41157197, 2025). "BMAL1 ablation inhibits the expression of CD36 and PPARγ signaling and attenuates hepatic steatosis." (PMID 40083324, 2025). "–11 The expression of CD36 is not only significantly upregulated in patients with fatty liver but also positively correlates with the liver’s fat content in these patients." (PMID 39774047, 2025). "CD36 promotes the uptake of free fatty acids (FFAs) by hepatocytes, increasing intracellular lipid accumulation and leading to hepatic steatosis." (PMID 41200186, 2025). "In the context of liver diseases, CD36 has been shown to participate in both intercellular and interorgan crosstalk, contributing to the progression of conditions such as fatty liver disease, hepatitis, and fibrosis." (PMID 39774047, 2025). "The activation of LXR by xenobiotics has been previously reported to lead to the development of hepatic steatosis through Cd36 upregulation." (PMID 38891072, 2024). "Overexpression of CD36 in hepatocytes increased FFAs uptake and TG storage; conversely, its deletion ameliorated hepatic steatosis and insulin resistance in DIO mice." (PMID 39436790, 2024). "As shown, CD36-knockout mice were protected against HFD-induced liver steatosis and reduced expression of FABP1 resulting in decreased intracellular lipid-binding capacity and reduced lipotoxicity." (PMID 36705799, 2024). "The introduction of KLF2 through adenovirus-mediated overexpression in healthy mice amplifies hepatic steatosis by increasing the expression of the Cd36 gene." (PMID 37949368, 2024). "A single administration of sgRubicon‐LNP reduced hepatic steatosis and lipid accumulation, regulated the glycerophospholipid metabolism pathway, and reduced CD36 expression, showcasing its potential to alleviate NAFLD." (PMID 38894572, 2024). "It has been demonstrated that hepatic overexpression of Cd36 in the liver improves glycogen homeostasis and alleviates liver steatosis induced by a HFD in mice." (PMID 39062955, 2024). "For example, global KO models of CD36 are resistant to carbohydrate-induced hepatic steatosis and have altered blood lipid parameters." (PMID 38716728, 2024). "Piperine exerts its favorable action in insulin resistance and hepatic steatosis through impairment of Lxr-α, Srebp1c, CD36, Chrebp-α, and Fas in high-fat diet mice model." (PMID 38200253, 2024). "Altered Cd36 expression is associated with NAFLD, and directly contributes to the development of fatty liver under conditions of elevated FFA by modulating the rate of FA uptake by hepatocytes." (PMID 38024380, 2023). "In NAFLD patients, in vivo, and in vitro studies, CD36 was upregulated and shown to drive hepatic steatosis by promoting DNL50–52." (PMID 37739978, 2023). "In male mice, PFOS induces fatty liver in a dose and time-dependent manner, by upregulating Cd36 and Lpl (lipoprotein lipase), inhibiting mitochondrial β-oxidation, and causing a shift of the hepatic proteome." (PMID 37242221, 2023). "Increased DKK1 in hepatic steatosis contributes CD36-mediated fatty acid uptake and insulin resistance." (PMID 36410795, 2023).